IL33 (interleukin 33)
Diseases named in the same sentence as IL33 in open-access papers (continued):
Sharing a sentence is not in itself a finding about the gene and the disease.
neurological diseases (21 papers, 2016 to 2025). "In contrast, IL-33 is deficient in some neurological diseases, such as in AD, and treatment with IL-33 can improve the cognitive and pathological symptoms in mouse models." (PMID 38542222, 2024). "Both the ST2 receptor and the protein IL-33 are expressed in the CNS by endothelial cells, neurons, astrocytes, and microglia and are linked to neurological diseases." (PMID 38542222, 2024). "In this review, the mechanisms underlying the dual role of IL-33 on cognitive function in neurological disorders have been discussed, but there are still some insufficiencies that need to be further investigated in the future." (PMID 35974336, 2022). "Moreover, IL-33 induces microglia activation / proliferation that is a hallmark of neurological disorders such as CNS inflammation." (PMID 28448579, 2017). "Results also demonstrated that proinflammatory molecules such as S100B, IL-17, IL-33, and neurological disease signaling pathways were upregulated, while protective pathways like aryl hydrocarbon receptor signaling were downregulated." (PMID 38719902, 2024). "The specific mechanisms through which IL-33 affects cognition in different neurological diseases still require further research." (PMID 35974336, 2022). "The significance of IL-33 as a possible therapeutic target for the preservation of cognitive function in neurological diseases of the CNS cannot be overstated." (PMID 35974336, 2022). "Apart from homeostatic development, IL-33 plays an important role in various neurological diseases, including neurodegenerative diseases, central nervous system infectious diseases, central nerve injury, and chronic pain." (PMID 36291105, 2022). "IL-33 has been proposed to play a role in the progression of several neurological diseases by modulating neuroinflammation." (PMID 35974336, 2022). "In this review, we summarize the regulatory mechanisms of IL-33 related to CNS inflammation in some neurological diseases." (PMID 35974336, 2022). "IL-33 is also prominently involved in the neuroinflammation of many neurological diseases such as Alzheimer's disease (AD) and multiple sclerosis (MS) through action mechanisms beyond immunomodulation." (PMID 30515150, 2018). "Interleukin-33 (IL-33) is increasingly being recognized as a key immunomodulatory cytokine in many neurological diseases." (PMID 29728120, 2018). "Similarly, disrupting the IL-33/ST2-AK2 signaling pathway inhibits microglia metabolic adaptation and phagocytosis, causing impaired neurodevelopment and neurological disorders." (PMID 39925809, 2025). "IL-33 is recognized as a key immunomodulatory cytokine in many neurological diseases." (PMID 36672270, 2023). "In recent years, the role of IL-33 in neurological diseases has attracted intense attention." (PMID 33854693, 2021). "Since targeting microbiota-gut-brain axis becomes new therapeutic strategy for neurological diseases, in the future, studies on the role of IL-33 from gut in microbiota-gut-brain axis might be emerging." (PMID 34079543, 2021). "Indeed emerging evidence from over a decade's research suggests that IL-33 acts as one of the key molecular signaling cues coordinating the network between the immune and CNS systems, particularly during the development of neurological diseases." (PMID 30515150, 2018). "IL-33 overexpression in CNS and spinal cord, including in astrocytes and oligodendrocytes, has been observed in several neurological disorders, but its precise regulation remains unclear." (PMID 28448579, 2017). "Therefore, the protective role of IL-33 may be applied in treating neurological diseases." (PMID 36291105, 2022). "Recent studies suggest that IL-33 and its receptor ST2 are involved in the pathogenesis of neurological diseases." (PMID 32859229, 2020). "This would enhance our understanding of the important roles the IL-33/ST2 signaling pathway plays in CNS homoeostasis and neurological disorders." (PMID 30515150, 2018).
neurological diseases (continued). "However, there are few studies that correlated with the participation of the IL-33/ST2 pathway in the brain, specifically, neurological disorders involving the central nervous system (CNS)." (PMID 29507527, 2018).
bacterial infections (20 papers, 2013 to 2025). "These in vivo findings were corroborated by our in vitro experiments, where IL-33-deficient BMDMs exhibited increased cell death upon fungal and bacterial infection." (PMID 40512033, 2025). "The role of IL-33 in host defense against bacterial infections was first shown in murine sepsis and skin models." (PMID 34960788, 2021). "The protective role of IL-33 against secondary bacterial infection post-IAV infection is further highlighted in asthmatics." (PMID 34960788, 2021). "Others have demonstrated that intestinal IL-33 is also regulated by bacterial infection and colonization." (PMID 33953267, 2021). "Collectively, these results indicate that IL-33 plays a crucial role during bacterial infection of cells and that it also contributes to immune defense against pathogens." (PMID 31640262, 2019). "Our findings appear to contradict the reports showing the beneficial role of IL-33 on bacterial infections, including cutaneous S. aureus infection." (PMID 29867945, 2018). "Extrapolating to others bacterial infections, IL-33/ST2 axis has apparent pleiotropic functions shaped by the local microenvironment." (PMID 29867945, 2018). "Our findings represent the first characterization of the signals regulating IL-33 expression in CF airway epithelial cells in response to a bacterial infection." (PMID 26793709, 2015). "Similar to our results, in another study in 2015, IL-33 mRNA expression increased with bacterial infection in stomach." (PMID 27014647, 2015). "To explore the role of IL-33 in bacterial infection we first evaluated the expression of IL-33 in skin from three S.aureus-infected human patients." (PMID 24586149, 2014). "Notably, interleukin-33 (IL-33) levels peaked early in bacterial infections but continued to rise throughout all time points in fungal endophthalmitis." (PMID 40512033, 2025). "Additionally, bone marrow-derived macrophages from IL-33−/− mice exhibited increased cell death in response to fungal and bacterial infection." (PMID 40512033, 2025). "However, additional experiments are needed to better characterize the reciprocal regulation of intestinal IL-33 and IL-17A levels during the course of bacterial infection." (PMID 33654214, 2021). "Expression of IL-1α and IL-33/ST2 has been reported in several bacterial infectious diseases." (PMID 27667993, 2016). "Therefore, it remains to be determined whether Amoxapine can induce IL-33 in Mtb infection in vivo or whether autophagy is involved in IL-33-mediated protection against other bacterial infections." (PMID 36129262, 2022). "Therefore, to mimic pulmonary exacerbations, we determined whether IL-33 was also upregulated during an acute bacterial infection." (PMID 26793709, 2015). "To address the physiological function of IL-33/ST2 signaling during intestinal bacterial infection, we first infected wild-type controls (WT) and ST2 knockout mice (St2−/−) as well as IL-33 knockout mice (Il33−/−) with CR for 10 days." (PMID 33654214, 2021). "Moreover, among the genes upregulated in pigs, genes involved in viral or bacterial infections, such as IFI44L, IL33, and RSAD2, were ranked at the top of the list." (PMID 38998110, 2024).
respiratory diseases (19 papers, 2019 to 2026). "IL-33 has been implicated in both protective and pathological roles across cardiovascular and respiratory diseases." (PMID 41564150, 2026). "We should recognize that there are currently many shortcomings in targeting the mechanism of action between IL-33 and type 2 inflammation-associated respiratory diseases." (PMID 39301028, 2024). "Multiple studies to date have implicated IL-33 in Alternaria-induced respiratory disease and have identified this fungal allergen as a potent stimulus for IL-33 secretion in BAL fluid in vivo." (PMID 33507882, 2021). "To date, IL-33/ST2 agents have robust safety data in respiratory disease trials (e.g. itepekimab, astegolimab), but oncology-specific phase I/II data are limited or unpublished." (PMID 41284319, 2025). "This review delves into the pivotal role and function of the IL-33 pathway as an “alarmin” in type 2 inflammation within respiratory diseases, exploring its clinical implications and potential for therapeutic interventions." (PMID 39301028, 2024). "The relationship between type 2 inflammation and IL-33 is significant, as IL-33 is considered a key regulator and “alarmin” in type 2 inflammation, particularly in respiratory diseases." (PMID 39301028, 2024). "Targeting these pathways to inhibit IL-33 expression and production has shown promising results in certain clinical trials, offering a new perspective on effective strategies for treating respiratory diseases driven by IL-33 in the future." (PMID 39301028, 2024). "The release of IL-33 activates Th2 responses, contributing to the onset and progression of inflammation in respiratory diseases." (PMID 39301028, 2024). "Looking ahead, further research into the role of IL-33 in respiratory diseases and the clinical application of IL-33-targeted therapies will be crucial." (PMID 39301028, 2024). "In the following sections, we evaluate the role played by HMGB1, IL-33, and non-coding genetic material in the onset of the most important respiratory diseases." (PMID 36675299, 2023). "In allergic and respiratory diseases, IL-33 activates type 2 innate lymphoid cells that elicit eosinophil recruitment and Th2 differentiation." (PMID 33884963, 2021). "IL-33 is highly expressed in pulmonary epithelial cells and has been shown to exacerbate airway inflammation and tissue damage in respiratory disease." (PMID 34685744, 2021). "Particularly important in the context of aggravation of chronic inflammation and progression of respiratory disease is IL-33 mediated influx of neutrophils and macrophages." (PMID 31057533, 2019). "Additional investigations are warranted to clarify the relationship between IL-33 and various respiratory disorders beyond the well-established conditions, paving the way for more targeted therapeutic approaches and a comprehensive understanding of IL-33 biology in respiratory pathology." (PMID 39301028, 2024). "By deepening our understanding of IL-33 regulatory mechanisms, we can develop more effective and personalized treatment approaches, ultimately providing better therapeutic options and improving quality of life for patients with respiratory diseases." (PMID 39301028, 2024). "Among discussed respiratory disorders, the role of IL-33 in OSA is the least known." (PMID 31057533, 2019). "In a preclinical house dust mite (HDM) mouse model of airway inflammation, itepekimab’s blockade of IL-33 significantly attenuated lung tissue injury and reduced inflammatory cell infiltration, supporting its potential to disrupt epithelial-driven inflammatory pathways in respiratory diseases." (PMID 40732309, 2025). "The purpose of our review is to highlight the alterations in respiratory diseases involving some alarmins, such as high mobility group box 1 (HMGB1) and interleukin (IL)-33, and their inter-relationships and relationships with genetic non-coding material, such as microRNAs." (PMID 36675299, 2023).
respiratory diseases (continued). "In aspirin-exacerbated respiratory disease, CysLT2R signaling on platelets could use RAGE/HMGB1 as a link to the downstream type 2 respiratory immunopathology and IL-33-dependent mast cell activation typical of aspirin-exacerbated respiratory disease." (PMID 35008546, 2021). "Furthermore, the level of eotaxin-3 was found to be closely related to IL-33 and TSLP levels which indicate respiratory diseases." (PMID 30778348, 2019).
immune diseases (17 papers, 2014 to 2025). "Recent studies have described IL33 as an emerging pro-inflammatory cytokine in the immune system, and IL33/ST2 gene polymorphisms have been implicated in the pathogenesis of various immune diseases." (PMID 33859633, 2021). "These Th1/Th2 responses abnormalities and the intervention of pro-inflammatory cytokines such as IL-33 were reported in condition related to an immune system disorder." (PMID 30577568, 2018). "The ST2/IL-33 signalling pathway has been reported to participate in the pathophysiology of numerous inflammatory and immune diseases." (PMID 25658420, 2015). "IL-33 is involved in the pathogenesis of immune diseases, such as rheumatoid arthritis and atopic dermatitis, and may reflect the degree of inflammation in patients with immune diseases." (PMID 24778632, 2014). "Clinical trials employing IL-33/ST2L neutralizing antibodies primarily target inflammatory diseases and immune disorders." (PMID 38778059, 2024). "IL-33 is an endogenous ligand for the ST2/T1 receptor, and depending on the cellular and cytokine context, participates in many immune diseases with dual, pro-inflammatory, or protective roles." (PMID 24778632, 2014). "Nevertheless, IL-33 levels in controls were lower than the detection limit, as expected in individuals without immune disorders." (PMID 40352809, 2025). "In addition, IL-33, which has been reported to play a major role in the induction of long-term immunosuppression, showed significant relief in the PICS + live Akk and PICS + pasteurized Akk groups, suggesting that Akk may have an important effect on immune dysfunction in mice with PICS." (PMID 36837813, 2023).
cardiac disease (16 papers, 2012 to 2025). "Elevated levels of sST-2 are associated with worse outcomes in cardiac diseases because sST-2 can block the protective effects of IL-33, leading to increased inflammation and fibrosis." (PMID 38912883, 2024). "The primary pathophysiological role of sST2 in cardiac disease is related to its protective interaction in the IL-33/sST2 axis." (PMID 39685669, 2024). "In this review, the pathophysiological effects of interleukins including the IL-1 family (IL-1, IL-18, IL-33, and IL-37), IL-2, IL-4, the IL-6 family (IL-6 and IL-11), IL-8, IL-10, and IL-17 on primary cell types of heart disease is elucidated." (PMID 37047468, 2023). "Mechanical stress or stretching of the myocardium by cardiac disease of any kind leads to increased release of interleukin-33 (IL-33) from fibroblasts, mast cells, endothelial cells and epithelial cells." (PMID 35330140, 2022). "Cardiac fibrosis is a common occurrence in heart disease due to mechanical overload, and IL-33 and ST2 expression are upregulated in rat cardiac fibroblasts subjected to cyclic mechanical strain." (PMID 38566909, 2022). "In cardiovascular research, IL-33 plays vital warning and mitigation roles and has variable functions among different types of heart disease." (PMID 31547872, 2019). "Perhaps elevated IL-33 negatively impacts heart disease by increasing a proinflammatory M2 macrophage population in the heart leading to remodeling and HF." (PMID 22013485, 2012). "This review will primarily focus on the pathophysiological effects of various interleukins including the IL-1 family (IL-1, IL-18, IL-33, IL-37), IL-2, IL-4, the IL-6 family (IL-6 and IL-11), IL-8, IL-10, IL-17 on primary cells of heart disease-CMs, FBs, ECs, and immune cells." (PMID 37047468, 2023). "The differences between IL-33 effects in fibrotic cardiac disease and fibrosis in other organs may stem from the necessity for scar tissue formation to compensate for the poor regenerative properties of cardiomyocytes." (PMID 38566909, 2022). "Both of the two studies highlighted the cardioprotective role of IL-33 in heart disease." (PMID 31547872, 2019). "Some factors may affect IL-33 levels, so we used logistic regression analyses to calculate the P values of IL-33 and IL-33/sST2 ratio adjusted by age, heart rate, blood pressure, pre-existing cardiac diseases, medications, and serum creatinine levels." (PMID 22682001, 2012). "ST2, has been best characterized in cardiac disease, whereby myocardial stretch or myocyte injury results in ST2 upregulation and secretion of soluble ST2 that binds with IL33 to regulate cardiac response to injury." (PMID 36572854, 2022). "In CHF patients, pre-existing cardiac diseases and medications used upon hospital admission did not affect IL-33 concentrations or the IL-33/sST2 ratio." (PMID 22682001, 2012).